AKAP3 (A-kinase anchoring protein 3)
Description:
Structural component of sperm fibrous sheath (By similarity). Required for the formation of the subcellular structure of the sperm flagellum, sperm motility and male fertility.
Synonyms: AKAP 110; CT82; FSP95; PRKA3; AKAP110; SOB1; HEL159; SPGF82
Tractability: PROTAC: ubiquitination databases record sites on it.
Gene: Protein-coding gene on chromosome 12 (4,613,383 to 4,649,072, reverse strand). Ensembl gene ENSG00000111254.
Subcellular location: Cytoplasmic vesicle, secretory vesicle, acrosome; Cell projection, cilium, flagellum
Subcellular location (Human Protein Atlas): Vesicles; Cytosol; Principal piece
Gene Ontology:
Molecular function: protein binding; protein kinase A binding
Biological process: acrosome reaction; cell surface receptor protein serine/threonine kinase signaling pathway; establishment of protein localization; flagellated sperm motility; intracellular protein localization; single fertilization
Cellular component: nucleus; sperm midpiece; sperm principal piece; cytoplasm; sperm fibrous sheath; acrosomal vesicle; motile cilium; sperm flagellum
Genetic constraint (gnomAD): Loss-of-function variants: 27 observed, 60.1 expected, observed/expected ratio (o/e) 0.45, 90% interval 0.33 to 0.62. The synonymous counts are far from expectation, so gnomAD's model fits this gene poorly and the ratio says little. Missense variants: 959 observed, 1,097.4 expected, observed/expected ratio (o/e) 0.87, 90% interval 0.83 to 0.92. Synonymous variants: 334 observed, 415.11 expected, observed/expected ratio (o/e) 0.8, 90% interval 0.74 to 0.88.
Homologues: Orthologues: chimpanzee AKAP3 (98% identical), macaque AKAP3 (94% identical), rabbit AKAP3 (80% identical), pig AKAP3 (78% identical), rat Akap3 (74% identical), mouse Akap3 (74% identical), dog AKAP3 (74% identical), guinea pig AKAP3 (70% identical). Paralogues in human: AKAP4 (35% identical), SPHKAP (16% identical), AKAP11 (15% identical).
Diseases named in the same sentence as AKAP3 in open-access papers:
AKAP3 is named in the same sentence as 24 diseases in open-access papers, as found by Europe PMC text mining. Sharing a sentence is not in itself a finding about the gene and the disease. The quoted sentences say what the papers report.
ovarian carcinoma (6 papers, 2012 to 2024). A malignant neoplasm originating from the surface ovarian epithelium. "It was shown that higher levels of AKAP3 expression were associated with a poor survivability of ovarian cancer patients." (PMID 37835834, 2023). "CT45 and AKAP3 are often highly expressed in advanced and high‐grade ovarian cancer and affect the overall survival and disease‐free survival of patients as independent prognostic factors of epithelial ovarian cancer." (PMID 38896069, 2024). "The efficacy of AKAP3 as a prognostic biomarker and an immunotherapy target has been demonstrated in ovarian cancer and hepatocellular carcinoma." (PMID 35322748, 2022). "We showed that AKAP3 mRNA expression was an independent and favorable prognostic factor in patients with poorly differentiated ovarian cancer." (PMID 23151147, 2012). "Previously, we showed that AKAP3 was a CT-like antigen, and that high AKAP3 mRNA expression was observed in ovarian cancer and the expression was correlated with the histological grade and clinical stage of the tumor." (PMID 23151147, 2012). "Some of the AKAPs considered to be CT genes in ovarian cancer include AKAP3 and AKAP4." (PMID 30609934, 2019). "Specifically AKAP3 have been shown to play a role in cell migration and invasion in ovarian cancer." (PMID 29433456, 2018). "Furthermore, high AKAP3 mRNA expression was observed in 43/74 (58%) of ovarian cancer specimens." (PMID 30609934, 2019). "The members of the CTA family in ovarian cancer mainly include MAGE, GAGE 1/2, LAGE‐1, NY‐ESO‐1, SSX, CT45, and TRAG‐3, which belong to the CT‐X antigen, and AKAP3/4, BAGE, BORIS, OY‐TES‐1(CT23), PRAME, PIWIL, HSP70‐2, SPAG9, and SP17, which belong to non‐X CT antigen." (PMID 38896069, 2024). "Moreover, separate studies in ovarian cancer demonstrated that the expression rates of Sp17 (CT22), SSX (CT5), AKAP3 (CT82), AKAP4 (CT99), and PLAC1 (CT92) were 43%, 26%, 58%, 89%, and 21%, respectively." (PMID 38896069, 2024). "CTA family members in ovarian cancer reported to date include MAGE genes, NY-ESO-1, SSX, and CT45, which are categorized as CT-X antigens, and BORIS, PRAME, PIWIL, and AKAP3/4, which are categorized as non-X CTAs." (PMID 30609934, 2019).
infertile (5 papers, 2019 to 2023). "In the present study, we used a combination of in silico approaches to develop a 3D model of AKAP3 and predict the consequences of nsSNPs that experimentally revealed in some infertile men with ISTS and oligoasthenoteratozoospermia." (PMID 35256641, 2022). "Overexpression of AKAP3 in normozoospermic infertile men suggests the accumulation of AKAP3, thus hampering the sperm capacitation process in UMI patients." (PMID 31336797, 2019). "In the present study ourcandidate genes, AKAP3 and PLOD3 were selected aftersequencing analysis and these mutations further characterized translational event after using bioinformatics toolsin the case of infertility." (PMID 32681621, 2020). "The present study explores acquaintance betweenchanges of nucleotides (frameshift and non-frameshiftmutation) in AKAP3 and PLOD3 gene and their transcriptional events (amino acids) in the cases of infertility." (PMID 32681621, 2020).
male infertility (4 papers, 2022 to 2025). The inability of the male to effect fertilization of an ovum after a specified period of unprotected intercourse. "In the AKAP family, AKAP3 and AKAP4 mutations were identified causing dysplasia of the fibrous sheath, presenting MMAF phenotypes and male infertility." (PMID 35955660, 2022). "Accordingly, as AKAP3 is involved in the emergence of male infertility, providing more structural insights and the impact of nsSNPs that cause protein functional diversity could help researchers elucidate the etiology of this disorder at the molecular level." (PMID 35256641, 2022). "As AKAP3 is involved in male infertility, providing more structural insights and the impact of mutations that cause protein functional diversity could elucidate the etiology of male fertility problems at molecular level." (PMID 35256641, 2022). "The results provide 3D structural information on the AKAP3 protein as a gene responsible for male infertility; in addition, it enables future investigations to target disease-associated mutations with more confidence and obtain more structural data about the etiology of male infertility." (PMID 35256641, 2022). "Previous studies have confirmed that a lack of AKAP3 induces asthenozoospermia and male infertility." (PMID 40089458, 2025).
breast carcinoma (3 papers, 2015 to 2022). "The cancer-testis antigen A-kinase anchor protein 3 (AKAP3) has been shown to have a strong association with breast cancer (BC)." (PMID 35322748, 2022). "In other words, the relationship between lack of AKAP3 expression in normal adjacent and poorer outcome is significantly detectable in the other subtypes of breast cancer than triple negative breast cancer (p = .01)." (PMID 26458542, 2015). "A number of these AKAPs have been reported to correlate with the occurrence of different cancer subtypes, including AKAP3 (ovarian cancer), AKAP4 (multiple myeloma), AKAP9 (breast cancer), AKAP10 (breast cancer) and AKAP13 (colorectal cancer and breast cancer)." (PMID 26272591, 2015).
hepatocellular carcinoma (2 papers, 2019 to 2022). A malignant tumor that arises from hepatocytes. "Meanwhile, AKAP3 and AKAP13 may be potential biomarkers for the diagnosis and prognosis of hepatocellular carcinoma." (PMID 31384238, 2019).
triple-negative breast carcinoma (2 papers, 2015 to 2022). An invasive breast carcinoma which is negative for expression of estrogen receptor (ER), progesterone receptor (PR), and human epidermal growth factor receptor 2 (HER2). "In an investigation of 162 tumor and normal tissues of breast, lack of AKAP3 expression was observed to be significantly associated with triple-negative breast cancer, breast tumor size, tumor stage, and 5-year disease-free survival." (PMID 36303815, 2022).
colon cancer (1 paper, 2012). "AKAP3 expression was also up-regulated in 2 colon cancer specimens." (PMID 23151147, 2012). "In this study, we performed SEREX analysis of colon cancer, and isolated a novel CT antigen, Tektin5 (TEKT5), in addition to a previously defined CT-like antigen, A kinase anchoring protein 3 (AKAP3)." (PMID 23151147, 2012).
cryptorchidism (1 paper, 2023). The failure of one or both testes of a male fetus to descend from the abdomen into the scrotum during the late part of pregnancy. "According to the extent of difference between cryptorchidism and normal testis, the expression of seven downregulated genes (PLCZ1, AKAP4, AKAP3, IZUMO1, SPAG6, CAPZA3, and ROPN1L) were further selected for validation by qPCR." (PMID 38027210, 2023).
epithelial ovary cancer (1 paper, 2015). "AKAP3 is a member of AKAP proteins that was reported to be expressed in epithelial ovary cancer." (PMID 26458542, 2015).
oligoasthenoteratozoospermia (1 paper, 2022). A form of male infertility that is characterized by a combination of low number or oligozoospermia, poor motility or asthenozoospermia, and abnormal shape or teratozoospermia of sperms. "Our unpublished findings in patients with immotile short tail sperm defect (ISTS) and oligoasthenoteratozoospermia showed some variations in the AKAP3 gene." (PMID 35256641, 2022). "For the first time, we used several bioinformatics approaches to analyze the impact of four nsSNPs on the AKAP3 structure that were present in men with ISTS and oligoasthenoteratozoospermia." (PMID 35256641, 2022).
osteomalacia (1 paper, 2022). Disorder caused by an interruption of the mineralization of organic bone matrix leading to bone softening, bone pain, and weakness. "Our results provide new biomarkers and therapeutic targets; miR-539-3p and AKAP-3 in bone disorders like XLH, Osteomalacia and Osteoporosis." (PMID 36267566, 2022).
varicocele (1 paper, 2015). A condition characterized by the dilated tortuous veins of the spermatic cord with a marked left-sided predominance. "We found that AKAP3 was underexpressed in the unilateral varicocele patients but present in high abundance." (PMID 25890347, 2015). "As a regulator of sperm motility, the reduced expression of AKAP3 in varicocele patients could contribute to the poor sperm motility seen in these patients." (PMID 25890347, 2015).
tumor (8 papers, 2012 to 2023). "AKAP3 was primarily expressed in the cytoplasm of tumor cells and was detectable in 136/145 (93.8%) BC tissue samples, including 79 cases with AKAP3 high expression patterns (++/+++) and 57 with AKAP3 low expression patterns (±/+)." (PMID 35322748, 2022). "The levels of AKAP3 mRNA expression was assessed in tumor compared with normal margins of a sub population of Iranian BC cases, and showed a significant lower expressions in tumors compared with normal tissues." (PMID 31286981, 2019). "The relationship between AKAP3 expression and ER, PR and Her2/neu status was analyzed in tumor and normal adjacent tissues separately." (PMID 26458542, 2015). "Chi-square analysis showed a significant relationship between the expression of AKAP3 in tumor tissues and tumor size (p=." (PMID 26458542, 2015). "In this study, we aimed to determine if there is a specific expression of AKAP3 in tumor compared to normal tissue." (PMID 26458542, 2015). "In this study expression of AKAP3 were investigated in tumor, normal adjacent and normal tissue of the breast in association with clinical features of the patients." (PMID 26458542, 2015). "However, there was an inverse correlation between the levels of AKAP3 expressions and tumor sizes and stages, highlighting that as a probable inhibitor of proliferation." (PMID 31286981, 2019). "The reduced expression of genes involved in stabilization of adherence proteins (AKAP5, 9, 11 and 12) as well as increase expression of genes associated with poor prognosis and proliferation (AKAP3 and AKAP8) strongly underscores the involvement of AKAP genes during tumor growth and dissemination." (PMID 29433456, 2018). "Also the proportion of patients in stage one who expressed AKAP3 in their tumor tissues was more than other stages." (PMID 26458542, 2015). "It means that patients with AKAP3 expression in normal adjacent tumor (28/63 of the patients) were associated with only 4/28 events compared to an event rate of 13/35 in the AKAP3 negative group." (PMID 26458542, 2015). "Based on these analyses, AKAP3 expression in tumor tissues was diminished in tumor size above 2 cm." (PMID 26458542, 2015). "There was a significant association between lack of AKAP3 expression in tumor tissues and triple negative status (p=." (PMID 26458542, 2015). "There was an association between lack of AKAP3 expression in tumor tissues and triple negative status (p=." (PMID 26458542, 2015). "The comparison of the mRNA expression levels of 32 genes of the 21 CTAs between relatively healthy and tumor ovarian tissue showed up-regulation in the expression level of the AKAP3, MAGEA4, PIWIL1, and PRAME genes in tumor samples." (PMID 37835834, 2023). "The analysis of the mRNA expression levels of 21 CTAs in healthy and tumor ovarian tissue showed an up-regulation in the expression level of AKAP3, MAGEA4, PIWIL1, and PRAME in tumor samples and a down-regulation in the expression level of CTAG1A, CTAG1B, MAGEC1, and PIWIL2." (PMID 37835834, 2023). "In addition, FSIP1 can bind to and activate cancer/testis antigen proteins (including CABYR, SPA17, AKAP3, AKAP4, and ROPN1) in the fibrous sheath in tumor cells, in turn promoting cancer progression." (PMID 28086239, 2017). "There was not such a relationship with the AKAP3 expression in tumor tissues (P = .8)." (PMID 26458542, 2015). "AKAP3 may act as inhibitor of proliferation since it was not expressed in higher stage and tumor size." (PMID 26458542, 2015).
cancer (4 papers, 2017 to 2022). A tumor composed of atypical neoplastic, often pleomorphic cells that invade other tissues. "AKAP3 is a member of A-kinase anchoring proteins, which has been recognized as a cancer-testis antigen for multiple types of cancer, including ovarian, hepatocellular, and colorectal." (PMID 36303815, 2022). "This oncogenic effect of AKAP3 has been reported in other cancer types." (PMID 35322748, 2022).
AKAP3 also shares sentences with these, for which no sentence is quoted: asthenozoospermia (1 paper); bone disorder (1); breast tumor (1); dysplasia of (1); male fertility (1); metastatic tumors (1); osteoporosis (1); ovarian tumors (1); periodontitis (1); testicular embryonic carcinoma (1).